PRC1 (protein regulator of cytokinesis 1)
Diseases named in the same sentence as PRC1 in open-access papers (continued):
Sharing a sentence is not in itself a finding about the gene and the disease.
prostate carcinoma (19 papers, 2014 to 2025). A carcinoma that arises from epithelial cells of the prostate gland. "Collectively, these findings highlight PRC1 as a critical biomarker of poor prognosis in prostate cancer, with strong associations to shorter RFS and higher Gleason scores." (PMID 40144021, 2025). "Upregulation of PRC1/2 is strongly linked to prostate cancer progression, lineage plasticity, and prostate cancer-specific mortality." (PMID 34716314, 2021). "Intriguingly, both PRC1 and BIRC5 have been demonstrated to be linked to M2 TAM infiltration in prostate cancer." (PMID 37647439, 2023). "This provides a model for studying how PRC1/RNF2 alters prostate cancer cells to influence metastasis." (PMID 32929562, 2021). "PRC1 has been associated with many malignant carcinomas, such as NPC, prostate cancer, and lung cancer." (PMID 32863767, 2020). "To further investigate the PRC1-independent BMI1 function in prostate cancer, we demonstrated that the BMI1-truncated mutant, BMI1ΔRING, which does not contain the RING domain and cannot interact with RING1B, still directly interacts with AR NTD." (PMID 29402932, 2018). "In this study, we discovered that BMI1, independently of the PRC1 complex, binds and stabilizes AR proteins to regulate the AR pathway in prostate cancer." (PMID 29402932, 2018). "This discovery conceptually advances our understanding of a novel, PRC1-independent role of BMI1 in prostate cancer progression through the AR pathway." (PMID 29402932, 2018). "Furthermore, functional assays were conducted to evaluate PRC1’s role in prostate cancer progression." (PMID 40144021, 2025). "Furthermore, some canonical PRC1 subunits or key components are also closely related to the malignant biological behavior of prostate cancer." (PMID 35892678, 2022). "Therefore, it is necessary to introduce PRC1 as a novel biomarker and therapeutic target into the clinical treatment of prostate cancer." (PMID 35892678, 2022). "Similarly, the strong upregulation of cell cycle progression, E2F/DREAM, and PRC1/2 pathways in tumors harboring ZNRF3 loss further supports a link between this tumor suppressor and pathways with established links to prostate cancer aggression." (PMID 34716314, 2021). "A recent study confirmed that the dysregulation of PRC1 might be responsible for biochemical recurrence in patients with prostate cancer, implying that PRC1 could be considered as a prognostic indicator." (PMID 33292244, 2020). "Likewise, overexpression of miR-203 inhibits breast and prostate cancer cells invasion through targeting 3'UTR of the mRNA of PRC1." (PMID 25004126, 2014). "Then, EED recruits polycomb repressive complexes 1 (PRC1) directly to the tri-methylated H3K27 loci and enhances PRC1-mediated H2A ubiquitin E3 ligase activity, indicating a potential role for SELENBP1 as an epigenetic exchange factor in prostate cancer." (PMID 36386843, 2022). "Interestingly, PRC1 has been reported to reverse the recruitment of M2 TAMs and regulatory T cells in the TME of prostate cancer to overcome immune evasion." (PMID 37647439, 2023). "Briefly, shRNA-silenced prostate cancer cells from PtenPC−/−Smad4PC−/− lacking functional PRC1 were injected into nude mice and metastasis to the bone and liver was reduced." (PMID 32929562, 2021). "In several studies on prostatic cancer, CBX family members, including CBX7, were shown to facilitate PRC1-mediated transcriptional repression by targeting the complex to tri-methylated lysine 27 of histone H3, inducing chromatin compaction, DNA methylation and repression of the underlying genes." (PMID 28388562, 2017). "Notably, a recent study in prostate cancer indicated that CBX2- and CBX8-containing PRC1 promotes the progression of prostate cancer to a highly aggressive neuroendocrine tumor subtype." (PMID 27449098, 2016).
prostate carcinoma (continued). "However, BMI1 exerts also some important oncogenic effects in prostate cancer cells through PRC1-independent mechanisms, involving direct binding to AR and consequent inhibition of MDM2-mediated AR degradation and sustained AR signaling in prostate cancer cells." (PMID 31366128, 2019). "Taken together with observations in other types of cancer, it seems likely that the PRC1 and specifically, CBX2, are novel therapeutic targets not only for HGSOC, but potentially for breast and prostate cancers." (PMID 30478317, 2018). "This is partly reflected in the TCGA expression profile where the expression of other PRC1/2 complex proteins does not change to the extent as compared to EZH2 in normal prostate and prostate cancer." (PMID 25115397, 2014).
lung carcinoma (18 papers, 2012 to 2025). "In this paper, we have found an essential function of KDM2B as a component of variant PRC1 complex during TGF-β-induced EMT of A549 lung cancer and Panc1 pancreatic cancer cell lines." (PMID 33779563, 2021). "Loss of PRC1 leads to the accumulation of bi- and multi-nucleated cells in lung cancer, which further supports its role as the major central spindle organizer in cytokinesis." (PMID 30881920, 2019). "We show that mitotic kinesins and the microtubule-associated protein PRC1 are overexpressed in lung cancer cell lines." (PMID 29435157, 2018). "Building upon our previous findings, which identified PRC1 as a risk factor in lung cancer with low DNA methylation level, this study demonstrates that TET2 is responsible for the demethylation and transcriptional activation of PRC1 in NSCLC cells by interacting with BACH1." (PMID 40665337, 2025). "Additionally, in gastric and lung cancers, the high expression of PRC1 has often been associated with early lymph node metastasis and poor prognosis." (PMID 35387129, 2022). "We find that the microtubule-associated protein PRC1 (protein required for cytokinesis 1), which plays a key role in organizing anti-parallel microtubule in the central spindle in cytokinesis, is overexpressed in lung cancer cell lines compared to normal cells." (PMID 29435157, 2018). "The protein regulator of cytokinesis 1 (PRC1) is a prognostic marker characterized by low DNA methylation in lung cancer." (PMID 40665337, 2025). "Increased expression of PRC1 promotes tumor proliferation and cell cycle progression in lung cancer." (PMID 39002386, 2024). "In this study, we tried to clarify the involvement of PRC1 components in the regulation of TGF-β-induced EMT of A549 lung cancer and Panc1 pancreatic cancer cell lines." (PMID 33779563, 2021). "Mechanistically, we provide evidence that depletion of PRC1 in lung cancer cells results in accumulation of bi- and multinucleated cells, consistent with its role as key player of central spindle organization which is essential for cytokinesis." (PMID 29435157, 2018). "We found that mitotic kinesins and PRC1 are expressed at higher levels in lung cancer cell lines compared to control cell lines." (PMID 29435157, 2018). "Quantification showed that PRC1 inhibits the proliferation of all five lung cancer cell lines in a dose-dependent manner." (PMID 29435157, 2018). "We therefore next investigated the effect of depletion of PRC1 in five different human lung cancer cell lines and in immortalized BJ fibroblast cells, which served as an untransformed control cell line." (PMID 29435157, 2018). "Examination by microscopy and quantification showed that silencing of PRC1 strongly increased the number of bi- and multinucleated cells in all five lung cancer cell lines, consistent with its known function in mitosis and cytokinesis." (PMID 29435157, 2018). "Lentiviral delivered, inducible RNAi of PRC1 demonstrated that proliferation of lung cancer cell lines strongly depends on PRC1." (PMID 29435157, 2018). "Another recent study reported a similar dependency of Wnt/ßcatenin target genes on PRC1 in lung cancer cell lines." (PMID 29435157, 2018).
lung carcinoma (continued). "Expression of the kinesins and of PRC1 was analyzed in a panel of human lung cancer cell lines by immunoblotting." (PMID 29435157, 2018). "Together these data establish the microtubule-binding protein PRC1 as potential target for therapy of lung cancer." (PMID 29435157, 2018). "Instead we suggest that the dependency of lung cancer cell lines on PRC1 is a consequence of its requirement for central spindle formation and cytokinesis." (PMID 29435157, 2018). "We performed expression analysis of PRC1 with 4 microarray datasets from the Hou, Selamat, Su, and Landi lung cancer groups that were downloaded from Oncomine." (PMID 28646916, 2017). "Similarly, in lung cancer, radioresistance-related signatures also predict patient outcomes and immune status, identifying TOP2A, CDH3, ASPM, CENPF, SLC2A1, and PRC1 as potential detection biomarkers for early lung cancer." (PMID 41041339, 2025). "Further studies have found that PRC is an miR-1-3p target, and inhibiting PRC1 expression may have an anti-lung cancer effect." (PMID 36185280, 2022). "Together these data establish PRC1 as a potential target for therapy of lung cancer." (PMID 29435157, 2018). "Furthermore, we demonstrate that depletion of PRC1 strongly inhibits the proliferation of five different human lung cancer cell lines due to the induction of apoptosis and senescence." (PMID 29435157, 2018). "Interestingly, a recent study suggested a similar regulation of Wnt/ß-catenin signaling by PRC1 in lung cancer cell lines." (PMID 29435157, 2018). "Next, we asked whether expression of PRC1 is of any clinical significance for human lung cancer by examining previously published microarray data sets." (PMID 29435157, 2018). "Whether PRC1 has additional functions independent from regulation of mitosis and cytokinesis in lung cancer cells remains to be shown." (PMID 29435157, 2018). "(A) PRC1 gene expression is upregulated in lung carcinomas compared to normal lung tissues." (PMID 28646916, 2017). "In conclusion, PRC1 could represent a novel target for therapy of lung cancer." (PMID 29435157, 2018). "Immunohistochemistry data of the three model gene proteins (MRPL51, SLK, PRC1) were retrieved from the HPA database and their expression was found to be upregulated in lung cancer." (PMID 35982906, 2022). "A signature of genes including CDC20, CCNB1, CDC2, CDKN3, MAD2L1, PRC1 and RRM2, were prognostic for 5-year survival in over 400 lung cancer cases, and interestingly, CDC20, CDC2, CCNB1 were also highly overexpressed in the aggressive case." (PMID 22905093, 2012). "In addition, we also analyzed the mRNA expression of PRC1 in LUAD tissues using two microarray datasets from the Hou and Selamat lung cancer groups, which were downloaded from Oncomine." (PMID 30881920, 2019). "In conclusion, our data do not support PRC1 as a target or regulator of Wnt/ß-catenin signalling in lung cancer cell lines." (PMID 29435157, 2018). "First, we find that PRC1 is not induced by Wnt3a in lung cancer cell lines." (PMID 29435157, 2018). "However, our data reported here do not support a role for PRC1 in Wnt/ß-catenin signalling in lung cancer cells." (PMID 29435157, 2018).
lung adenocarcinoma (15 papers, 2013 to 2025). A carcinoma that arises from the lung and is characterized by the presence of malignant glandular epithelial cells. "To investigate the molecular mechanism underlying the oncogenic role of PRC1 in lung adenocarcinoma, we utilized NGS to assess the gene expression profiles of PRC1-depleted A549 cells and control cells." (PMID 28646916, 2017). "Notably, Next Generation Sequencing (NGS) was performed to investigate the molecular mechanism underlying the oncogenic role of PRC1 in lung adenocarcinoma." (PMID 28646916, 2017). "Moreover, studies have shown that PRC1 is associated with poor prognosis in lung adenocarcinoma, and thus inhibition of PRC1 may be a promising therapeutic target for lung adenocarcinoma." (PMID 36744262, 2023). "Additionally, loss of PRC1 induces G2/M phase arrest and apoptosis in vitro, PRC1 expression is associated with high Wnt/β-catenin potency in lung adenocarcinoma patient tissues and PRC1 protein overexpression was an independent poor prognostic factor for lung adenocarcinoma patients." (PMID 28646916, 2017). "As well as, PRC1 promotes lung adenocarcinoma cells proliferation, metastasis and tumorigenesis by activating the Wnt/β-catenin signaling pathway." (PMID 36744262, 2023). "In this study, our findings were consistent with previous studies in which PRC1 was highly expressed in lung adenocarcinoma and correlated with patient prognosis." (PMID 35816352, 2022). "PRC1 contributes to tumorigenesis of lung adenocarcinoma and plays a key role in the activation of the Wnt/β-catenin signaling pathway." (PMID 34299277, 2021). "Increased expression of PRC1 is correlated with a poor prognosis of human lung adenocarcinoma patients." (PMID 29435157, 2018). "Strikingly, lung adenocarcinoma patients with tumors with high expression PRC1 showed a significant shorter survival compared to patients with low expression." (PMID 29435157, 2018). "In this investigation, we limited our scope to the oncogenic role and molecular mechanism of PRC1 in lung adenocarcinoma." (PMID 28646916, 2017). "PRC1 mRNA and protein expressions were upregulated in lung adenocarcinoma tissues compared to adjacent normal lung tissues." (PMID 28646916, 2017). "In summary, we determined for the first time the expression pattern and molecular mechanism of PRC1 in lung adenocarcinoma." (PMID 28646916, 2017). "These in vivo and in vitro results synergistically demonstrated that PRC1 plays an important regulatory role in lung adenocarcinoma metastasis." (PMID 28646916, 2017). "The correlation between PRC1 overexpression and clinicopathological factors of lung adenocarcinoma patients was assessed." (PMID 28646916, 2017). "Our data implied that PRC1 depletion limited the proliferation and invasion of lung adenocarcinoma cells in vitro and lowered tumor development and lung metastasis in vivo." (PMID 28646916, 2017). "PRC1 protein overexpression correlated with lymph node metastasis and was an independent poor prognostic factor for lung adenocarcinoma patients." (PMID 28646916, 2017). "Herein, we demonstrated that both mRNA and protein expressions of PRC1 were upregulated in lung adenocarcinoma tissues compared with adjacent normal lung tissues." (PMID 28646916, 2017). "To additionally verify the interaction between PRC1 and Wnt/β-catenin pathway relevant genes, we contrasted the protein expression patterns in tumor specimens obtained from patients with lung adenocarcinoma." (PMID 28646916, 2017). "Next, we examined the effect of PRC1 knockdown on the proliferation of three lung adenocarcinoma cells." (PMID 28646916, 2017). "The protein expression level of PRC1 in lung adenocarcinoma tissues was significantly greater than those in the corresponding nearby healthy tissues (P < 0.005)." (PMID 28646916, 2017).
lung adenocarcinoma (continued). "This suggests that PRC1 plays a role in lung adenocarcinoma cell development through the regulation of the cell cycle progression at the G2/M phase." (PMID 28646916, 2017). "We further determined that overexpression of PRC1 protein correlates with lymph node metastasis and is an independent poor prognostic factor for lung adenocarcinoma patients." (PMID 28646916, 2017). "Quantitative reverse-transcription polymerase chain reaction (qRT-PCR), Western blotting and Immunohistochemical staining (IHC) were used to evaluate and contrast the PRC1 expression profile in lung adenocarcinoma and adjacent normal lung tissues." (PMID 28646916, 2017). "First, PRC1’s expression profile was evaluated in lung adenocarcinoma tissues and contrasted with nearby healthy lung tissues." (PMID 28646916, 2017). "Collectively, these data suggested that PRC1 was critical for lung adenocarcinoma cell proliferation in A549 and HBE cells." (PMID 28646916, 2017). "We further verified that the tumorigenesis impact of PRC1 in lung adenocarcinoma cells was by the induction of G2/M phase cell cycle arrest and apoptosis." (PMID 28646916, 2017). "(B) PRC1 expression was confirmed by qPCR in lung adenocarcinoma cells (A549, SPC-A1, and H1299) transduced with lentiviruses expressing scramble (shControl) or PRC1-targeting (shPRC1–1 and shPRC1–2) shRNA." (PMID 28646916, 2017). "Additionally, the tumorigenesis impact of PRC1 in lung adenocarcinoma cells was verified via in vitro and in vivo metastasis and tumorigenesis assays." (PMID 28646916, 2017). "We further investigated whether PRC1 regulates lung adenocarcinoma cells motility in vitro using transwell migration assays." (PMID 28646916, 2017). "Moreover, the present study demonstrates that reduced expression of PRC1 suppresses the proliferation and invasion of lung adenocarcinoma cells in vitro and in vivo." (PMID 28646916, 2017). "Our results provide a basis for the concept that overexpression of PRC1 in human lung adenocarcinoma may be important in the acquisition of an aggressive and poor prognostic phenotype." (PMID 28646916, 2017). "This investigation offers confirmation that PRC1 is a prognostic and promising therapeutic biomarker for people with lung adenocarcinoma and takes on a key part in the activation of the Wnt/β-catenin pathway in lung adenocarcinoma development." (PMID 28646916, 2017). "Therefore, PRC1 down-regulation inhibits the growth of established lung adenocarcinoma in xenografts." (PMID 28646916, 2017). "Notably, Next Generation Sequencing (NGS) revealed that PRC1 was involved in the Wnt/β-catenin signaling pathway of lung adenocarcinoma tumorigenesis." (PMID 28646916, 2017). "The preliminary mechanistic studies indicate that PRC1 may play a critical role in the control of lung adenocarcinoma aggressiveness by activating the PRC1/Wnt/β-catenin feedback loop." (PMID 28646916, 2017). "We then examined the clinical use of PRC1 in the prognosis of lung adenocarcinoma." (PMID 28646916, 2017). "We then used the Annexin V/PI assay to determine whether silencing PRC1 expression could induce apoptosis in lung adenocarcinoma cells." (PMID 28646916, 2017). "Moreover, β-catenin, c-Myc, c-Jun, Cyclin D2 and PRC1 protein expression were examined by IHC in tissue sections of 25 lung adenocarcinoma." (PMID 28646916, 2017). "We examined the clinical use of PRC1 in lung adenocarcinoma prognosis." (PMID 28646916, 2017). "However, the precise molecular mechanisms underlying the role of the Wnt/β-catenin signaling pathway in the regulation of PRC1 in lung adenocarcinoma remain unclear and will be investigated in future studies." (PMID 28646916, 2017). "Therefore, our results suggest that increased PRC1 expression may play an important role in lung adenocarcinoma initiation and progression." (PMID 28646916, 2017).